ZMAT3 (zinc finger matrin-type 3)
Diseases named in the same sentence as ZMAT3 in open-access papers (continued):
Sharing a sentence is not in itself a finding about the gene and the disease.
tumor (continued). "Single-cell analysis dissected that ERRFI1, ETS1, NDRG1, and ZMAT3 were expressed in the tumor microenvironment." (PMID 37600707, 2023). "Inhibiting ZMAT3 may enhance the sensitivity of tumor cells to chemotherapy and radiotherapy by inducing DNA damage." (PMID 39664194, 2024). "Only the expressions of ERRFI1, ETS1, NDRG1, and ZMAT3 were detected in the tumor microenvironment." (PMID 37600707, 2023). "We therefore hypothesized that the function of Zmat3 in tumorigenesis may be context dependent, influenced by genetic background, cell type or oncogenic drivers specific to each tumor." (PMID 33082333, 2020). "One of these, ZMAT3 (rat synonyms PAG608 and WIG1), has been found to increase apoptosis and decrease growth of tumour cells." (PMID 19200380, 2009). "In LUAD, ZMAT3 suppresses tumor growth by inhibiting cell proliferation without inducing cell apoptosis." (PMID 39664194, 2024).
tumor (continued). "Conversely, several genes, such as ZMAT3 and DGAT1, demonstrated reduced or absent staining in tumor tissues relative to normal tissues, indicating potential tumor-suppressive functions." (PMID 40299459, 2025).
cancer (12 papers, 2009 to 2026). A tumor composed of atypical neoplastic, often pleomorphic cells that invade other tissues. "However and consistent with our findings, other investigators also showed that ZMAT3 and p21 expression is induced with similar kinetics in both normal and cancer cells, indicating that the effects of ZMAT3 may depend on the cellular context." (PMID 35146866, 2022). "Here, we discovered a function of ZMAT3 in inhibiting transcription of HKDC1, a hexokinase that regulates glucose metabolism and mitochondrial respiration in human cancer cells." (PMID 41842937, 2026). "Again, annotation to OMIM revealed that several cancer-related genes were involved in these LOH regions (MLH1, ZMAT3, ADCY7, PIK3CA)." (PMID 20428235, 2010).
infection (3 papers, 2020 to 2022). The state of being infected such as from the introduction of a foreign agent such as serum, vaccine, antigenic substance or organism. "Two of these upregulated genes are related to damage response and the prevention of infection by retroviruses (ZMAT3 and ZC3HAV1, respectively)." (PMID 32317694, 2020).
ZMAT3 also shares sentences with these, for which no sentence is quoted: abortion (2 papers); Huntington disease (2); adenocarcinoma (1); autism (1); bacterial infection (1); brain ischemia (1); cervical adenocarcinoma (1); cervical tumor (1); cognitive deficits (1); colon cancer (1); COVID-19 (1); developmental verbal dyspraxia (1); Gilles de la Tourette syndrome (1); HCMV infection (1); leiomyoma (1); lung squamous cell carcinoma (1); metabolic disease (1); neurodegenerative disease (1); osteosarcoma (1); papillary thyroid cancer (1); prostate carcinoma (1); T cell lymphoma (1); thyroid cancer (1); thyroid tumor (1); type 2 diabetics (1); viral infection (1); Zinc deficiency (1).